RN7SL398P (RNA, 7SL, cytoplasmic 398, pseudogene)
Gene: Miscellaneous RNA gene on chromosome 10 (33,288,304 to 33,288,601, reverse strand). Ensembl gene ENSG00000244356.
Homologues: Orthologues: chimpanzee Metazoa_SRP (99% identical), macaque Metazoa_SRP (93% identical). Paralogues in human: RN7SL2 (85% identical), RN7SL1 (84% identical), RN7SL3 (84% identical), RN7SL145P (83% identical), RN7SL296P (83% identical), RN7SL655P (83% identical), RN7SL118P (82% identical), RN7SL732P (82% identical), RN7SL711P (81% identical), RN7SL122P (81% identical), RN7SL126P (81% identical), RN7SL664P (81% identical), and 707 more.